CCND1 (cyclin D1)
Diseases named in the same sentence as CCND1 in open-access papers (continued):
Sharing a sentence is not in itself a finding about the gene and the disease.
bladder cancer (continued). "Our current studies indicated that p100 could increase LARP7 transcription, which hosts miR-302d in the intron, and p100-mediated activation of miR-302d expression was crucial for its suppression of Cyclin D1 protein translation in bladder cancer cells." (PMID 27095572, 2016). "MiR-16 inhibits bladder cancer proliferation by targeting Cyclin D1." (PMID 25888950, 2015). "One recent study demonstrated that metformin could arrest bladder cancer cells in the G0/G1 phase with concomitant decreases in the expression of cyclin D1, CDK4 and E2F1, which is verified again in our study." (PMID 26245871, 2015). "It has been reported that exogenous KLF5 expression increased cell cycle transition and up-regulated cyclin D1 in TSU-Pr1 bladder cancer cells, and accelerated degradation of KLF5 protein performed by curcumin impaired tumor growth of bladder cancer cells in vitro and in vivo." (PMID 26544730, 2015). "Thus, the down regulation of STAT3/cyclin D1 signaling can account for the cell cycle arrest in the G0/G1 stage and reduced G1/S phase transition in the bladder cancer cells treated with metformin." (PMID 26245871, 2015). "In addition, p21, p27, Cyclin D1 and Ki67 were found to be dysregulated in miR-135a- overexpressing bladder cancer cells, indicating a putative correlation between miR-135a and the PI3K/Akt signaling pathway." (PMID 25888950, 2015). "However, in the field of bladder cancer, the search for a prognostic value of cyclin D1 expression has produced different results." (PMID 24602161, 2014). "Moreover, exogenous KLF5 expression increased cell cycle transition and up-regulated cyclin D1 in TSU-Pr1 human bladder cancer cells." (PMID 25170806, 2014). "Ten studies reported data on cyclin D1 expression and OS in bladder cancer." (PMID 24602161, 2014). "Our in vivo study also showed that metformin could decrease the expression levels of cyclin D1 in a bladder cancer xenograft model and suggests that metformin may be a valuable potential therapeutic agent to block bladder tumor growth." (PMID 24351837, 2013). "Therefore, inhibition of cyclin D1 seems to be an effective molecular target for the treatment of bladder cancer." (PMID 24351837, 2013). "CCND1 amplified bladder cancers may be sensitive to CDK4 inhibitors; ERBB2 amplified tumors may be sensitive to lapatinib, trastuzumab, or T-DM1; and MDM2 inhibitors are in current clinical development." (PMID 23593348, 2013). "Our results also demonstrated that metformin could arrest bladder cancer cells in the G0/G1 phases with concomitant decreases in the expression of cyclin D1, CDK4 and E2F1." (PMID 24351837, 2013). "Our results suggested that copy number changes of CCND1 could be used as a biomarker to detect chromosome instability in bladder cancer." (PMID 20540739, 2010). "Amplification of CCND1 or alterations in c-myc/CCND1 early in bladder cancer may have clinical relevance in promoting and predicting progression to detrusor-muscle-invasive transitional cell carcinoma." (PMID 12237776, 2002). "However, rates of amplification of CCND1 were 19%, marginally higher than a previous study of bladder cancer by Southern blotting which reported amplification rates of 11q13 of 11%." (PMID 12237776, 2002). "Additionally, we analyzed the protein expression of Cyclin D1 in bladder cancer cells." (PMID 40083696, 2025). "To further determine whether the SKP1 pathway promotes the proliferation of bladder cancer cells consistent with circGLIS3-Cyclin D1, we transiently overexpressed SKP1 in circGLIS3 shRNA stable cell lines and used flow cytometry to detect the cycle change of bladder cancer cells." (PMID 33656636, 2022).
bladder cancer (continued). "The predicted results suggested that circGLIS3 may adsorb miR-1273f like a sponge, so that the binding of miR-1273f to SKP1 decreases, thereby promoting the expression of SKP1 and increasing the expression of Cyclin D1, and ultimately promoting the proliferation of bladder cancer cells." (PMID 33656636, 2022). "Several aCGH studies of bladder cancer have been published to date and provide the identification of a number of genomic regions of DNA amplification that contain known or candidate oncogenes including cyclin D1 (CCND1) on 11q13, ERBB2 on 17q21, MDM2 on 12q14–q15, and E2F3 on 6p22." (PMID 25178926, 2014). "Our in vitro and in vivo results demonstrate that curcumin inhibits the cell growth of bladder cancer at least partially through inhibiting Hippo pathway effectors YAP/TAZ, which induce the accelerated degradation of KLF5 protein and subsequently cause the downregulation of cyclin D1." (PMID 25170806, 2014). "Thus downregulation of cyclin D1 may be essential for the anti-cancer effects of metformin in bladder cancer cells." (PMID 24351837, 2013). "However, the chromosomal regions that contain c-myc and CCND1 are genetically unstable, which may be of significance in the development of muscle-invasive bladder cancer." (PMID 12237776, 2002). "Through activating IL11-STAT3 signaling and CCND1, DANCR promoted the metastasis and proliferation of bladder cancer cells." (PMID 41602364, 2026). "METTL3 is known to promote cell cycle progression in cancers like HNSCC and bladder cancer and it regulates cell cycle markers such as CDK2 (cyclin-dependent kinase 2) and Cyclin D1 in gastrointestinal stromal tumors." (PMID 40338154, 2025). "Together, Cyclin D1, C-MYC, and miR-146b form an interconnected regulatory network that drives the rapid proliferation and progression of bladder cancer, making them potential targets for therapeutic intervention." (PMID 40224178, 2025). "Then, we performed WB experiments on bladder cancer cell lines with knockdown or overexpression of IGF2BP3 to investigate the expression changes of multiple cyclin proteins CDK2, CDK4, CDK6, and CCND1." (PMID 40083693, 2025). "In agreement with prior literature, significant copy number alterations involved deletion of CDKN2A/B, leading to cell cycle dysregulation, and focal amplifications in CCND1 and MDM2, which are well-documented events in bladder cancer." (PMID 41373802, 2025). "In bladder cancer, KNSTRN affects the cell cycle by regulating the expression of cyclin D1 and CDK2." (PMID 38198023, 2024). "Stable knockdown of miR-1273f expression can effectively inhibit G0/G1 phase arrest caused by knocking down circGLIS3 and promote the proliferation of bladder cancer cells and promote the expression of SKP1 and cyclin D1." (PMID 33656636, 2022). "miR-502-5p inhibited the expression of CCND1, NOP14, and DNMT3B, the targets of miR-502-5p, by reducing cell migration in bladder cancer." (PMID 34288816, 2021). "Recently, Chen and colleagues reported that lncRNA DANCR directly interacted with LRPPRC and guided LRPPRC protein to bind and stabilize the mRNAs of CCND1, PLAU, and IL-11, resulting in enhanced proliferation, migration, and invasion of bladder cancer cells." (PMID 34671012, 2021). "Two additional genes, CCND1 and RB1, identified in the bladder cancer signaling network are known biomarkers, and the third gene identified in the bladder cancer signaling network (CDK4) is a known inhibitor of bladder cancer." (PMID 29912931, 2018).
bladder cancer (continued). "Thus we checked change of cyclin D1/E and found Rab27A was able to induced cyclin D1 and cyclin E. cyclin D1 and cyclin E play pivotal roles during G1-S checkpoint and their overexpression correlate with malignant growth and aggressive phenotype of bladder cancer cells." (PMID 29088864, 2017). "Accordingly, three bladder cancer cell lines (T24, 5637, and HT1376) representative of two distinct carcinogenesis pathways to invasive cancer (FGFR3/CCND1 and E2F3/RB1) were used." (PMID 27835695, 2016). "In bladder cancer, cell cycle regulatory proteins, such as CABLES, Ki67, and cyclin D1, probably play a role in the tumorigenesis of bladder cancer." (PMID 25978027, 2015). "Cyclin D1 protein expression has been reported to be correlated with both poor and good prognosis, partially since a single study might be too underpowered to detect a possible small effect of cyclin D1 expression on bladder cancer prognosis, especially when the sample size is relatively small." (PMID 24602161, 2014). "Exogenous KLF5 promotes TSU-pr1 bladder cancer cell growth in vitro and in vivo, which is consistent with our results that knockdown of KLF5 leads to the down-regulation of cyclin D1 and a decrease of the cell proliferation of 5637 bladder cancer cells." (PMID 25170806, 2014). "Our study is the first report in the literature regarding the simultaneous CCND1 amplification in DM and HSR in bladder cancer cells." (PMID 20540739, 2010). "Moreover, we found that MIR4435-2HG exerted versatile effects on bladder cancer,i.e., MIR4435-2HG promoted tumor cell proliferation and regulated the expression of multiple cell cycle regulators, such as CCND1 and BRCA2." (PMID 37355516, 2023). "Cyclin D1 induction of CIN is in mouse hepatocytes, lymphoid tumors and bladder cancer." (PMID 36358806, 2022). "Published research manifested that DANCR (differentiation antagonizing non-protein coding RNA) promoted metastasis and proliferation in bladder cancer cells by enhancing IL-11-STAT3 (interleukin-11-signal transducers and activators of transcription-3) signaling and CCND1 expression." (PMID 33931059, 2021). "Morin decreases CDK2, CDK4, cyclin D1, and cyclin E via modulation of the p21/WAF1 pathway, suppressing c-Jun N-terminal kinase (JNK) and AKT phosphorylation, and preventing MMP-9 expression by repressing NF-κB, SP-1, and AP-1 in EJ bladder cancer cells." (PMID 33996570, 2021). "Similarly, another study also reported decreased expression levels of cyclin D1, cyclin E, CDK2 and CDK4 in bladder cancer cells in a dose-dependent manner (0, 25, 50, 100 μg/mL) after 24 h of fucoidan treatment (undefined species source)." (PMID 32046368, 2020). "Moreover, in bladder carcinoma cells, maspin modulated HDAC1 target genes, including cyclin D1, p21, MMP9, and vimentin." (PMID 31861435, 2019). "Maspin acts as an HDAC1 inhibitor, which may modulate the p21, cyclin D1, MMP9, and vimentin expressions in bladder carcinoma cells." (PMID 31861435, 2019). "In addition to bladder cancer, FGFR3 translocations and amplification of the CCND1 and MYC genes are common in multiple myeloma." (PMID 29423038, 2018). "We downregulated C14orf166 using siRNAs, and both quantitative RT-PCR and western blotting revealed that Cyclin D1 expression was downregulated significantly and P21 and P27 expression was upregulated significantly upon C14orf166 knockdown in RT4 bladder cancer cells." (PMID 26905879, 2016).
bladder cancer (continued). "qRT-PCR analysis found the expression of NF-κB-targeted genes, including CCND1, Bcl-2, MMP9 and VEGF were upregulated once overexpression of URGCP/URG4, whereas knockdown of URGCP/URG4 significantly inhibited the levels of these genes in bladder cancer cells." (PMID 26429874, 2015). "Our analysis combined the outcomes of 2,591 bladder cancer patients from 15 individual studies, indicating that altered cyclin D1 expression was not correlated with OS, RFS, and DFS of bladder cancer patients, but was with PFS (HR: 0.54, 95% CI: 0.32–0.92)." (PMID 24602161, 2014). "Four studies reported data on cyclin D1 expression and RFS in bladder cancer." (PMID 24602161, 2014). "Seven studies reported data on cyclin D1 expression and PFS in bladder cancer." (PMID 24602161, 2014). "Thus, our study connected YAP and KLF5 in bladder cancer, and the pro-proliferative YAP/TAZ/KLF5/cyclin D1 axis was also revealed." (PMID 25170806, 2014). "Two studies reported data on cyclin D1 expression and DFS in bladder cancer." (PMID 24602161, 2014). "In bladder cancer (BLCA), NSUN2, IGF2BP2, YTHDC1, ALKBH5, TRDMT1, and ZC3H13 were identified, with NSUN2—a 5-methylcytosine (m5C) writer—previously shown to promote tumorigenesis and cancer stemness by stabilizing CCND1 mRNA and driving epithelial–mesenchymal transition." (PMID 40565233, 2025). "CytoNCA plug-in analysis showed that the PI3K-Akt signaling pathway (degree = 9) may be the key pathway in the treatment of bladder cancer by COP, and AKT1 (degree = 12), GSK3B (degree = 10), CASP3 (degree = 10), TNF (degree = 8) and CCND1 (degree = 8) were considered to be the main hub targets." (PMID 41287122, 2025). "Therefore, to elucidate the molecular mechanisms of DLX6-AS1 in regulating bladder cancer progression, we focused on the Wnt/β-catenin signaling pathway, and determined the expression of several key factors including β-catenin, GSK-3β c-myc and cyclin D1." (PMID 31787849, 2019). "In the same manner, other potential oncogenes, such as CCND1, not in the 6p22 amplicon but yet frequently altered in bladder cancer, could have additional interactions." (PMID 24231253, 2013). "Lastly, while we focused on the miR-146b-induced regulation of Cyclin D1 and C-MYC, additional miRNAs or transcription factors may cooperate in modulating this axis, warranting further investigation into the broader regulatory network involved in bladder cancer progression." (PMID 40224178, 2025). "Furthermore, this study confirmed that TEX10 silencing inhibited the β-catenin and level activation of cyclin D1 and c-Myc, demonstrating that TEX10 might promote the tumorigenesis of urinary bladder carcinoma via increasing XRCC6 level to enhance the signaling of Wnt/β-catenin." (PMID 34966825, 2021).
cervical carcinoma (145 papers, 2002 to 2026). A carcinoma arising from either the exocervical squamous epithelium or the endocervical glandular epithelium. "m6A-associated downregulation of miR-193b promoted cervical cancer aggressiveness by targeting CCND1." (PMID 36058934, 2022). "The results suggest that cyclin D1 in the cytoplasm is an independent prognostic factor and that high cyclin D1 expression is associated with poorer survival in cervical cancer." (PMID 34335935, 2021). "Accumulating evidence demonstrated that cervical cancer specimens harboring raised CCND1 levels were linked to lower overall patient survival." (PMID 34178650, 2021). "m6A associated downregulation of miR-193b promotes cervical cancer aggressiveness by targeting CCND1." (PMID 34178650, 2021). "Many case-control studies reported that patients with CCND1 A allele or AA genotype have an increased risk and poor disease outcome in a number of cancer types, such as nasopharyngeal carcinoma and cervical cancer." (PMID 29511472, 2017). "Loss of RB1 function, which is a well known phenomenon in cervical cancer leads to expression of Cyclin D1, over-expression/amplification of CDK4, and/or loss of the CDKN1B, CDKN2A and CDKN2B." (PMID 26701206, 2016). "We performed a meta-analysis to investigate the association between CCND1 G870A polymorphism and cervical cancer risk." (PMID 25204741, 2014). "PubMed, Embase and CNKI data were researched to conduct a meta-analysis on the associations between CCND1 G870A polymorphism and cervical cancer risk." (PMID 25204741, 2014). "We therefore performed the comprehensive meta-analysis to clarify the relationship between the CCND1 G870A polymorphism and cervical cancer risk with all published studies." (PMID 25204741, 2014). "The same authors also showed that patients bearing the CCND1 A/A and A/G genotypes (of cyclin D1) displayed a 1.811-fold increased risk of cervical cancer (95% CI = 1.150–2.852, P = 0.0098)." (PMID 22091418, 2011). "Also, TMS-TMF-4f suppressed both constitutive and IL-6-inducible levels of phosphorylated STAT3 (p-STAT3) and associated proteins such as Mcl-1, cyclin D1, survivin, and c-Myc in both cervical cancer cells." (PMID 31816985, 2019). "Notably, expression of a key cell cycle-associated protein, cyclin D1, was significantly downregulated in TN-treated cervical cancer cells, which might be a key mechanism of TN-induced cell cycle arrest and proliferation inhibition." (PMID 39282148, 2022). "Nevertheless, some current studies have shown that the presence of HPV infection combined with CCND1 G870A polymorphism might increase the risk of cervical cancer, which was consistent with the published reports with positive expression of HPV infection in cervical cancer." (PMID 25204741, 2014). "High cyclin D1 expression has been correlated with advanced tumor stage, lymph node metastasis, and poorer overall survival in cervical cancer patients." (PMID 41464230, 2025). "KIF18B is shown to activate the Wnt/β‐catenin pathway in cervical cancer, reducing Cyclin D1 expression." (PMID 40405535, 2025). "The deregulation of cyclin expression, especially cyclin D1, cyclin E, and cyclin A, has been frequently observed in cervical cancer and high-grade cervical intraepithelial neoplasia (CIN2/3) and contributes to uncontrolled cell proliferation." (PMID 41464230, 2025). "Further down-regulation of miR-193b encourages the proliferation and invasion of cervical cancer cells by targeting and promoting CCND1-encoding cyclin D1 (CyclinD1) mRNA expression." (PMID 39904996, 2025). "We found a study that reported overexpression of miR-195 inhibits cervical cancer progression by targeting CCND1 and MYB." (PMID 39095857, 2024).